IL9 (interleukin 9)
Diseases named in the same sentence as IL9 in open-access papers (continued):
Sharing a sentence is not in itself a finding about the gene and the disease.
tumor (continued). "Th9 cell-derived IL-9 and IL-21 can enhance the ability of CD8+ T and NKT cells to secrete IFN-γ, thereby promoting tumor killing." (PMID 32228589, 2020). "Tumor-infiltrating T, B, and NK cell levels and plasma concentrations of Th1 (IL-2, IFN-γ, and TNF-α), Th2 (IL-4, IL-5, IL-6, and IL-10), Th9 (IL-9), and Th17 (IL-17A, IL-17F, IL-21, and IL-22) cytokines were evaluated." (PMID 32802733, 2020). "Here the authors show that replacing TGFβ with IL-1β induces a distinct IL-9+ CD4+ population that have strong cytotoxic and anti-tumor activity in preclinical mouse models." (PMID 30914642, 2019). "Cytokine analysis in tumor patients revealed comparatively lower levels in IL-16, IL-18, CXCL8 (IL-8), IL-9, and CXCL10 (IP-10), indicating that the higher T cell numbers were not accompanied by increased T cell activity." (PMID 30740106, 2019). "And now, in light of evidence that PUVA also downregulates IL-9 in CTCL patients and that anti-IL9 treatment reduces tumor growth in a CTCL mouse model, IL-9 targeting has become a promising therapeutic intervention in patients with CTCL." (PMID 30250844, 2018). "We further detected 20 serum cytokines in tumor-bearing mice and 7 cytokines were significantly different between GLE treated and model groups, including IFN-γ, IL-1β, IL-4, IL-9, IL-12, RANTES and TNF-α." (PMID 30139984, 2018). "Altogether, these studies suggest that TH9 cells trigger IL-9 and IL-21-dependent, CD8-dependent anti-tumor responses that favor tumor elimination." (PMID 27832300, 2017). "TH9-derived IL-9 leads to upregulation of p21 and TRAIL, thus inducing tumor cell cycle arrest and apoptosis upon activation of IL-9R." (PMID 27832300, 2017). "IL-9 produced by CD4+T cells is responsible for increased survival and function in myeloid DCs, which contribute to anti-tumor immunity." (PMID 27589682, 2016). "Furthermore, the levels of Interleukin-9 (IL-9) correlated positively with the density of general T cells and CTL in the whole tumor tissue as well as in distinct compartments." (PMID 40497965, 2025). "Th9 cells primarily rely on IL9 and IL21 to perform their anti-tumor function." (PMID 41019045, 2025). "Additionally, VV that drives IL-9 gene expression demonstrated prolonged viral persistence in tumors and increased CD4+ and CD8+ T-cell infiltration in the tumor microenvironment in mice." (PMID 40867310, 2025). "Although in vitro studies show that IL-9 has minimal effects on proliferation, it enhances the expression of vascular endothelial growth factor (VEGF) and increases microvascular density, thereby promoting tumor growth via enhanced vascularization." (PMID 41302515, 2025). "Studies have indicated the absence of IL-9 or PU.1 inactivation in T cells resulted in decreased tumor growth, implicating a pro-tumoral role of PU.1+ Th9 cells." (PMID 40895524, 2025). "Similarly, tumor markers CA125 and CA199, RBC, and the inflammatory cytokine IL-9 exhibited statistically significant intergroup differences." (PMID 41040659, 2025). "Furthermore, we found higher levels of CXCL10, IL-9, and CCL4 in cases with higher numbers of T cells in direct contact with tumor cells, and thus their potential targets, while in these cases, VEGF levels were reduced." (PMID 40497965, 2025). "According to existing literature, IL-9 binds to heterodimer receptors, activating the Janus kinase(JAK)-STAT, insulin receptor substrates(IRS), and MAPK signaling pathways, thereby directly stimulating tumor cell proliferation." (PMID 38840908, 2024). "In the current study, we asked whether and how the intratumoral expression of IL-9 using an oVV modulates the TME and what antitumor effects it might have in murine tumor models." (PMID 38473379, 2024). "Conversely, strong negative correlations with tumor burden were found with IL-2 (r=-0.6589, p = 0.0275) and IL-9 (r=-0.7606, p = 0.0066)." (PMID 39623404, 2024).
tumor (continued). "Interestingly, we observed an increase in IL-9 at day 7 post CAR T cell injection for anti-FOLR1 CAR candidates A and E, correlating with the faster tumor-killing kinetics." (PMID 38254822, 2024). "These pathways may also indirectly regulate IL-4, IL-9, and TNF-α, as these cytokines frequently interact with metabolic and proliferative pathways within the tumor microenvironment." (PMID 39727942, 2024). "Cytotoxic T lymphocyte (CTL) responses induced by the treatment in tumor-bearing mice were also markedly reduced in the absence of IL-9." (PMID 37189417, 2023). "In turn, the IL9-polarized macrophages secreted chemokines, including CCL3, CCL4, CXCL9, and CXCL10, to recruit antitumor T cells, NKs, DCs, and macrophages to infiltrate the tumor." (PMID 36968220, 2023). "Tumor-localized IL9 also polarized TAMs toward M1 in vivo and made them release CCL3/4 and CXCL9/10 to recruit antitumor immune cells, including T and natural killer cells, into the tumor microenvironment." (PMID 36968220, 2023). "This indicates that in this model, IL-9 induced an anti-tumor immune response through action on tumor cells, rather than through immunomodulation." (PMID 37189417, 2023). "To date, no clinical trial has been approved to analyze the anti-tumor efficacy of IL-9 in patients with cancer." (PMID 36936961, 2023). "We can infer that the amount of IL9 reaching the tumor region was small in the systemic circulation model and not evenly distributed within the tumor." (PMID 36968220, 2023). "Specifically, Tc9 cell-derived IL-9 can activate STAT3 to increase fatty acid oxidation and mitochondrial activity, which imparts Tc9 cells with reduced lipid peroxidation and the resistance to tumor or ROS-induced ferroptosis." (PMID 36003368, 2022). "Furthermore, recent work shows that IL-9-polarized CAR T cells leading to reduced exhaustion and increased anti-tumor activity, demonstrate less differentiated phenotype with reduced frequency of EM cells." (PMID 35406703, 2022). "IL-9 target cells in NSCLC consisted of IL-9R+ tumor cells and tumor-infiltrating lymphocytes." (PMID 35514957, 2022). "Th9 cells are a recently identified subset of CD4+ T cells that produce IL-9 in response to TGF-β and IL-4 in vitro and have been shown to participate in the pathogenesis of allergic inflammation and asthma and play roles in anti-tumor immunity." (PMID 36241625, 2022). "Flow cytometry analysis clearly showed an upregulation of IL-9R expression in the tumour tissue of wild-type and IL-9 knockout mice as compared with control tissue lacking tumours." (PMID 35793807, 2022). "Therefore, referring to macrophage categorization, mast cells are divided into anti-tumor MC1 and pro-tumor MC2 based on TNF, granzyme B (GZMB), IL9, VEGF-A, and C-X-C motif chemokine ligand 8 (CXCL8) expression." (PMID 36726981, 2022). "While IL-9 alone was not sufficient to induce tumor migration, macrophages from both WT and Il9r−/− mice promoted tumor migration to a similar extent." (PMID 35778404, 2022). "As FoxP3+ Treg cells are known to suppress anti-tumor immunity in NSCLC, these findings suggested that IL-9 derived from Treg cells and TIL might control immune responses and tumor growth." (PMID 35514957, 2022). "Similar to the LL/2 model, we observed in additional experiments that the number of mice with no tumor was induced in the absence of IL-9." (PMID 35514957, 2022). "More importantly, 67% of the IL-9 heterozygous and 50% of the IL-9 knockout mice were tumor free as opposed to 40% in the wild type mice group, indicating an anti-tumoral effect of IL-9 deficient mice." (PMID 35514957, 2022). "Moreover, we found that IgG control treatment in tumor model resulted in decreased number of CD4+ and CD8+ T-bet+TNF-α+ T cells which were induced by the anti-IL-9 antibody treatment." (PMID 35514957, 2022). "In this direction, our analysis of the tumor compartment alone shows no prognostic significance for IL9 or IL18 concentrations." (PMID 36131941, 2022).
tumor (continued). "Cells in all conditions exhibited comparable percentages of cell death and proliferation, suggesting the IL-9-macrophage axis has no direct impact on tumor cell proliferation or cell death in these models." (PMID 35778404, 2022). "IL-9 could also be produced by CD8+ Tc9 cells, Vδ2 T cells, and mastocytes, and it plays a role in anti-tumor immunity." (PMID 35211408, 2022). "Tc9 cell–derived IL-9 activated STAT3, upregulated fatty acid oxidation and mitochondrial activity, and rendered Tc9 cells with reduced lipid peroxidation and resistance to tumor- or ROS-induced ferroptosis in the tumor microenvironment." (PMID 35192544, 2022). "While it is possible AMs contribute to the IL-9-dependent tumor promoting phenotype in early tumor development, we did not observe significant changes of AM numbers comparing WT and Il9r−/− mice." (PMID 35778404, 2022). "Blocking IL-9 signaling reduced the expression of granzyme B and perforin in human CD8+ T cells, and stimulation with recombinant IL-9 enhanced the cytotoxicity of tumor-specific mouse CD8+ T cells." (PMID 33777008, 2021). "IL-9, one of the most recent entries in the list of cytokines with effects on CLL, is secreted by several immune cells in many disease contexts where it shows both anti-tumoral and pro-tumoral effects that depend on the specific tumor subtype." (PMID 34944921, 2021). "IL-9 level was also significantly down-regulated by liver-infiltrating HBV-specific Th9 cells in tumor site compared with in non-tumor site (P=0.013, SNK-q test)." (PMID 34177894, 2021). "Tumour size (T) and metastasis to the neck lymph nodes (N) (according to TNM classification), tumour differentiation grade (G), stage, smoking experience, and distribution of IL-9 rs1859430 genotypes were effective variables in the LSCC-specific survival." (PMID 33803218, 2021). "We delineate a comprehensive network of IL-9 regulation in Th cells by the interactions among different micro-environmental cues and metabolites with the EGFR-HIF1α signaling cascade and its potential implications in anti-tumor immunity." (PMID 34075041, 2021). "In addition, the ectopically expressed membrane-bound form of IL-9 (MB-IL-9) has immune rejection and toxic effects on CT26 tumor cells and can magnify the cytotoxic effects of CD4+ T cells and CD8+ T cells." (PMID 32228589, 2020). "We observed that exposure to tumor cells significantly enhanced the production of IL9 by Th9 and Tc9 but not Th1 or Tc1 CAR-T cells." (PMID 33214555, 2020). "Mast cells induce infiltration of MDSCs to tumor and induce their IL-17 secretion; MDSC-derived IL-17 attracts Tregs indirectly and potentiates their suppressive activity and IL-9 production; IL-9 in turn promotes the survival and tumor-promoting function of mast cells." (PMID 32793192, 2020). "The anti-tumor functions of Th9 cells is mediated by IFN-γ and IL-21 while IL-9 could also directly kill tumor cells, thus we tested whether PP2A mediated inhibition of Th9 cells abrogates its anti-tumor functions via suppressing IFN-γ production." (PMID 32620893, 2020). "In vitro, IL-9 can directly induce proliferation and inhibit apoptosis in the DLBCL cell lines LY1 and LY8, promote the survival of DLBCL cells, and reduce the sensitivity of tumor cells to chemicals by upregulating the P21CIP1 gene in tumor cells." (PMID 32228589, 2020). "In two clinical trials in China, it was described that patients with CRC had lower expression of IL-9 in plasma and CRC tumor tissue, and the expression level was correlated with the tumor stage: the more advanced the tumor stage, the lower the IL-9 serum level." (PMID 33371444, 2020). "In addition, IL-9 boosted the production of CCL20 in lung tissue, leading to the recruitment of CCR6+ DCs and CCR6+ CD8+ T cells to the tumor bed." (PMID 32508847, 2020).
tumor (continued). "It seems that the mechanism underlying the tumour growth inhibition in low and high dose DCG treated mice is different, as more IFNγ secreting T cells were infiltrated to the tumour site in high dose DCG treated mice, while more IL-9 secreting T cells were observed in low dose DCG treated mice." (PMID 31183361, 2019). "Altogether, our data indicated that low-dose p38 inhibitor treatment restricts tumor progression by enhancing generation of IL-9-producing cells without systemic toxicity in vivo." (PMID 31266950, 2019). "In addition to GM-CSF and TNF-α, MC also store and release several other potential anti-tumor mediators including reactive oxygen species (ROS), prostaglandin D2 (PGD2), interleukin-9 (IL-9), and heparin." (PMID 30833944, 2019). "Notable inhibition of tumor progression by SB203580 was observed, which was IL-9 dependent." (PMID 31266950, 2019). "In parallel, low-dose p38 inhibitor restores Fas-mediated TH9 cell induction in vitro and in vivo, and greatly suppresses tumor progression via IL-9 without inducing systemic adverse effects." (PMID 31266950, 2019). "Th9 cells can stimulate epithelial cells by IL-9 to produce CCR6 ligand CCL20, which recruits immature DCs (iDCs) and other APCs into tumor region, and then these APCs present antigen to activate CD8 cytotoxic T lymphocyte (CTLs) to kill tumor cells." (PMID 31414895, 2019). "The tumor-infiltrating lymphocytes (TILs) in the WT → WT mice demonstrated an enhanced percentage of IL-9-producing CD4+ T cells but no increased percentages of IFN-γ- or IL-17A-producing CD4+ T cells or Tregs." (PMID 31266950, 2019). "Interestingly, they also noted that DTA-1 enhanced IL-21 secretion from CD4 T cells in an IL-9-independent manner and proposed that DTA-1 enhances anti-tumor responses through TH9 cell-derived IL-9 and, possibly, IL-21." (PMID 27832300, 2017). "Finally to define the functional relationship between Th9/IL-9 and dectin-1-activated DC-induced antitumour effects, OT-II mice with established B16-OVA tumours were treated with OVA peptide-pulsed CurDCs in the presence or absence of anti-IL-9." (PMID 27492902, 2016). "Flow cytometry analysis of lung infiltrating OT-II cells showed that Foxp3+ T cells, but not IL-9+ Th9 cells, were induced in tumour-bearing mice in control Ig-treated mice." (PMID 26365427, 2015). "Due to its role in recruiting non-malignant infiltrating cells, IL-9 makes a crucial contribution to tumor survival, migration and metastasis." (PMID 24722378, 2014). "It was demonstrated that Th9 cell infiltration within tumor tissue promoted an immunoevasive environment, characterized by reduced cytotoxic activity of CD8+ T cells, which expressed high levels of inhibitory receptors, including PD-1, in the presence of IL-9-producing Th cells." (PMID 39325360, 2025). "For example, in solid tumors such as non-small cell lung cancer and breast cancer, IL-9 can induce the immunosuppressive effects of Treg cells and mast cells in the TME, promote angiogenesis, or upregulate the expression of PD-1 molecules on cytotoxic T lymphocytes to enhance tumor immune escape." (PMID 41346580, 2025). "Non-hematopoietic models demonstrate potent anti-tumor activities of IL-9 and Th9 cells." (PMID 41030439, 2025). "To further enhance the anti-tumor efficacy of Xcl1-E6E7, we explored the immunization of mice with the Xcl1-E6E7 plasmid in combination with several plasmids expressing interleukins known to stimulate T cell proliferation and memory formation, including IL-7, IL-9, IL-21, and IL-33." (PMID 39852828, 2025). "Similarly, macrophages in metastatic UVM showed strong enrichment for cytokines like Adiponectin, Prolactin, IL7, IL10, IL15, IL9, IL31, APRIL, Persephin, and IL22, highlighting their role in creating a pro-tumorigenic environment through immune modulation and support of tumor growth." (PMID 39916959, 2024). "IL-9 enhanced M2 but not M1 macrophage-induced tumor cell migration." (PMID 35778404, 2022).
tumor (continued). "Interestingly, anti-tumor activity of Th9 cells in these studies was dependent on IL-21, but not IL-9." (PMID 36389679, 2022). "To determine whether circulatory levels of IL9 or IL18 in PDA patients differ from healthy individuals and whether they potentially reflect systemic tumor responses, we compared IL9 and IL18 blood levels of our patient cohort with an age-matched control group of healthy individuals (n=30)." (PMID 36131941, 2022). "We observed an induction of IL-9 production by tumor infiltrating lymphocytes (TIL) and a subset of FoxP3+ regulatory T cells in the tumoral region of NSCLC patients and identified tumor infiltrating T cells, FoxP3+ Treg cells and tumor cells as IL-9R expressing target cells for IL-9 signaling." (PMID 35514957, 2022). "As such, IL-33-dependent tumour growth in gp130F/F mice correlated with the expansion of mast cell subsets but could not be definitively linked to ILC2, notwithstanding IL-9 (an ‘ILC2-related’ cytokine) as a putative mechanism for MMC expansion in this model." (PMID 35677533, 2022). "The seemingly conflicting effect from that report could be due to gating of differing populations of macrophages, the ectopic effects of IL-9 in the tumor microenvironment, or a lack of context if a specific cell location is required for optimal IL-9 delivery." (PMID 35778404, 2022). "Because our analyses of tumor-bearing mice treated with cGAMP also revealed an increased frequency of IL-9-producing CD4 T cells in the tumor microenvironment, we finally evaluated the contribution of other CD4 T cell-derived cytokines (IL-9, IL-17, and IL-4) to the anticancer effects of cGAMP." (PMID 35091453, 2022). "Thus, the induction of IL-6 function reversed the protective phenotype of IL-9 knockout mice and restored tumour induction to levels indistinguishable from wild-type mice." (PMID 35793807, 2022). "Thus, JAK3 promotes survival and proliferation of malignant T cells and expression of proto-oncogenes/oncomiRs and cytokines (IL-5, IL-9, IL-13, IL-17F and LTA), some of which are growth factor to malignant T cells while others modulate the tumour micro-environment (TME) and anti-cancer immunity." (PMID 33466582, 2021). "However, anti-4-1BB antibody, IL-2, and IL-9 failed to reduce tumor burden in the Myc-CaP CRPC tumor model." (PMID 34771735, 2021). "Therefore, the results of the present study showing the absence of differences in IL-9 rs1859430, rs2069870, rs11741137, rs2069885, and rs2069884 variants distribution between LSCC tumour patients and sex-matched control subjects are apprehensible." (PMID 33803218, 2021). "IL-9 could induce recruitment of DCs and leukocytes via the CC-chemokine ligand 20- (CCL20-) CC-chemokine receptor 6 (CCR6) axis and promote DCs to migrate to tumor-draining lymph nodes (TDLNs)." (PMID 33748292, 2021). "GITR-induced IL-9 promoted tumor-specific CD8+ cytotoxic T lymphocyte (CTL) response by upregulating the expression of costimulatory and MHC II molecules and increasing the crosspresentation capacity of GITR ligand- (GITRL-) expressing DCs in a melanoma tumor model." (PMID 33748292, 2021). "High cholesterol in the tumour environment can suppress CD8+ T cells, promoting the transcription of exhaustion markers like PD-1 through the ER stress sensor X-box-binding protein 1 (XBP1) and inhibiting interleukin-9 (IL-9) expression through LXR sumoylation." (PMID 33047740, 2020). "Additionally, they found that CurDC-immunized mice showed stronger tumor-specific CTL activity, which could be inhibited by the administration of the IL-9-neutralizing antibody." (PMID 32508847, 2020). "However, these roles are not absolute: in some solid tumors, IL-9 also has the function of promoting tumor development." (PMID 32228589, 2020).